APOE (apolipoprotein E)
Diseases named in the same sentence as APOE in open-access papers (continued):
Sharing a sentence is not in itself a finding about the gene and the disease.
atherosclerosis (continued). "The prominent role of IL-1β in atherosclerosis is evidenced by the results of IL-1β gene ablation in ApoE–/– mice and by neutralizing antibody therapy against IL-1β that decreased the rate of recurrent cardiovascular events, as shown in the CANTOS study." (PMID 33329050, 2020). "To investigate the potential role of T cells reactive to the mouse cationic antimicrobial peptide mCRAMP in the male apoE−/− mouse model of atherosclerosis, we first tested if T cells were reactive to mCRAMP." (PMID 33123157, 2020). "In one study, ApoE−/− mice were infused with Ang II, resulting in increased atherosclerosis as well as the expected increase in hypertension." (PMID 32630530, 2020). "In order to assess the role of Jcad in atherosclerosis, we crossed Jcad−/− mice with hyperlipidaemic ApoE−/− mice." (PMID 31584065, 2020). "The aim of the study is to investigate the effects of Taoren Honghua drug on inflammation and atherosclerosis in ApoE knock-out mice and RAW264.7 cells." (PMID 32765273, 2020). "Altering self-reactive immune responses to COL6A1 in apoE–/– mice resulted in differential effects on atherosclerosis burden with sex as a determinant of outcome." (PMID 32373127, 2020). "Animal studies have shown that deletion of Angptl3 can reduce atherosclerosis development in apolipoprotein E knockout mice." (PMID 32280540, 2020). "Here, we investigate basal autophagy in a mouse model of atherosclerosis, apolipoprotein E (ApoE)-knockout (KO) mice, and we analyze the role of autophagy in driving Tregs polarization." (PMID 32231663, 2020). "The apolipoprotein E knock out (ApoE−/−) mouse is one of excellent models of the mimicking human atherosclerosis, which shows the spontaneously occurring lesions distributed in the vasculature." (PMID 32685460, 2020). "Pharmacodynamics studies on ApoE-KO mice with atherosclerosis (AS) showed that PNS generated an obvious anti-AS action." (PMID 32382308, 2020). "Recently, intervention studies have been performed on smooth muscle cell (SMC) lineage, tracing ApoE−/− mice with advanced atherosclerosis using anti-IL-1β or IgG control antibodies." (PMID 32545788, 2020). "ApoE-/-Fbn1C1039G+/- develop atherosclerosis in response to a high-fat diet, and this process is accelerated compared to regular apoE-/- mice." (PMID 32428130, 2020). "Extensive atherosclerotic lesions were visible beneath the valve leaflet in the ApoE-/- C57B/L6J mice compared to the control, suggesting atherosclerosis was successfully induced in ApoE-/- C57B/L6J mice." (PMID 32611832, 2020). "Another study also showed long term exposure to nickel nanoparticles (NiNPs) viawhole-body inhalation system exacerbated atherosclerosis in ApoE KO mice." (PMID 33022979, 2020). "In an apolipoprotein E knockout murine atherosclerosis model, the knockdown of EPHA2 using adenovirus-carrying short hairpin RNA resulted in the attenuation of atherosclerotic lesion development." (PMID 32887275, 2020). "Whereas two studies suggest that ApoE/Nox1 double knockout mice developed less atherosclerosis one study observed the opposite." (PMID 32949971, 2020). "apoE–/– mice are characterized by severe hyperlipidemia and the spontaneous development of atherosclerosis." (PMID 32762716, 2020). "The subcutaneous injection of the lncRNA CDKN2B-AS1-overexpressing lentiviral vector into apoE-/- mice robustly mitigates atherosclerosis development by inhibiting ADAM10." (PMID 33154191, 2020).
atherosclerosis (continued). "Macrophage SR-A expression in macrophages is downregulated by treatment with intermedin, a novel member of the calcitonin gene-related peptide family: intermedin attenuates atherosclerosis plaque burden in APOE-null mice." (PMID 33182772, 2020). "This phenomenon is amplified in ApoE−/− mice, one of the most commonly used murine models of hypercholesterolemia-induced atherosclerosis." (PMID 39649554, 2020). "Here, we show that the cysteine analogue, ribose-cysteine, can enhance GSH and GPx activity in the apoE-/- mouse model of atherosclerosis resulting in protection from disease development." (PMID 32084149, 2020). "In our previous study, we found that TCDD and PCB coexposure in ApoE−/− mice enhanced atherosclerosis development." (PMID 32855961, 2020). "Heat-shock protein GroEL of F. nucleatum has been reported to induce the expression of monocyte chemokines and cell adhesion molecules, and to promote the progression of atherosclerosis in ApoE−/− mice." (PMID 32002588, 2020). "In ApoE-/- mice on a Western diet, an animal model of hyperlipidemia and atherosclerosis, we showed that this strain alleviated severe lipid accumulation and atherosclerosis, in conjunction with the shifted the gut microbial structure." (PMID 32806628, 2020). "Apolipoprotein E knockout (ApoE–/–) mice were first designed for atherosclerosis pathogenesis studies, because they exhibit a 5- to 10-fold increase in plasma cholesterol levels." (PMID 33536868, 2020). "We firstly investigated the in vivo effects of SiNPs exposure on atherosclerosis via intratracheal instillation of ApoE−/− mice fed a Western diet." (PMID 33008402, 2020). "CyPA stimulates migration and proliferation of VSMCs, expression of adhesion molecules in endothelial cells, and inflammatory cell chemotaxis, and promotes atherosclerosis in ApoE−/− mice." (PMID 33371312, 2020). "Given the pathophysiological role of ApoE in atherosclerosis and AD, we next investigated the blood–cerebrospinal fluid (CSF) barrier of the choroid plexus (ChP) region in ApoE-/- mice to determine the neuroprotective effects of THD." (PMID 33121058, 2020). "A comprehensive literature search using PubMed, Embase, and the Cochrane Library databases was performed to identify studies that assessed the effects of terpenoids on atherosclerosis in ApoE -/- mice." (PMID 31392210, 2019). "To examine possible changes in expression of the members of the miR-106b~ 25 cluster with the progression of atherosclerosis, we used the ApoE KO model." (PMID 31796057, 2019). "In accordance, FXR-/- ApoE-/- mice have increased blood levels of cholesterol and triglycerides, a more severe pro-atherogenic plasma lipoprotein profile, and a more severe atherosclerosis." (PMID 31892152, 2019). "A previous study has shown that inhibition of IDO1 can increase atherosclerosis in ApoE−/− mice, which raises concerns for the potential pharmaceutical application of IDO1 inhibitors." (PMID 31637003, 2019). "MiR-155 expression was also increased in high-fat diet-fed ApoE−/− mice and in patients with atherosclerosis and preeclampsia." (PMID 30765689, 2019). "In this study, CUMS ApoE-/- mice model with atherosclerosis was established, and HMGB1 inhibitor or TLR4 inhibitor was used to test its role in atherosclerosis under CUMS." (PMID 30881312, 2019). "The finding of reduced macrophage accumulation in atherosclerotic lesions and less arterial expression of IL1β in μMT−/− ApoE−/− mice is consistent with the reduced inflammation in atherosclerotic lesion, and decreased atherosclerosis in μMT−/− ApoE−/− mice." (PMID 31998318, 2019).
atherosclerosis (continued). "When Apoe-/- mice were transplanted with wild type bone marrow, apoE levels in the plasma increased and the hyperlipidemia and atherosclerosis exhibited a notable reduction, despite only low levels of apoE in the plasma." (PMID 31231209, 2019). "Other studies have demonstrated that injection of antagomir-155 attenuated atherosclerosis development and progression in ApoE−/− mice." (PMID 31139076, 2019). "The apoE−/− mice are a widely utilized animal model of atherosclerosis, since they spontaneously develop arterial lesions, dyslipidemia, and hypercholesterolemia, as well as changes in the liver resembling mild hepatic steatosis." (PMID 30925684, 2019). "Atherosclerosis in μMT−/− ApoE−/− mice that received wildtype B2 B cells increased by 109% as assessed by intimal lesion area." (PMID 31998318, 2019). "We observed that the adventitia of ApoE−/− mice undergoes major restructuring events during all stages of atherosclerosis: Both innate and adaptive immune cells accumulate adjacent to the neighboring atherosclerotic plaques." (PMID 31164888, 2019). "Increase in plasma GBB concentration was shown to be related to the development of atherosclerosis in apolipoprotein E knockout (ApoE-/-) mice." (PMID 31636806, 2019). "At first, we investigated the effects of SBP on atherosclerosis through measuring the size of plaque lesions in the entire aorta of the apoE−/− mice fed by HFD." (PMID 31379468, 2019). "Historically, ApoE knock-out mice were the first animal model of atherosclerosis established using gene technology methods." (PMID 31038578, 2019). "So far, only limited data on apoE knockout rats have been published, and findings about spontaneous atherosclerosis are contradictory." (PMID 31796798, 2019). "Increased numbers of circulating proinflammatory monocytes have been found in mouse models of atherosclerosis, such as ApoE−/− mice." (PMID 31653058, 2019). "Expression of IL-6 is regulated by IL-6 receptor and signal transducing protein gp130; IL-6 being a pro-atherogenic cytokine exacerbates the progression of atherosclerosis in ApoE-/- mice." (PMID 32082145, 2019). "In this context, NLC and RXP470.1-NLC were synthetized here, and we thoroughly characterized both nanoparticles and their biodistribution pattern in the ApoE-/- atherosclerosis mice model." (PMID 31561608, 2019). "On the other hand, as already mentioned, there are indications that germ-free mice have reduced plasma GABA levels and this is in accordance with the fact that germ-free ApoE-/- mice develop more atherosclerosis than conventional mice with the same genotype." (PMID 31892152, 2019). "In apoE-deficient mice, treatment with self-antigenic complexes, loaded DNA from CAD patients and antimicrobial peptide resulted in advanced atherosclerosis mainly due to the stimulation of pDCs." (PMID 31717832, 2019). "Hepatic overexpression of Bmal1 in liver-specific Bmal1-/- knockout and APOE-/- knockout mice can reduce hyperlipidemia and atherosclerosis." (PMID 31139087, 2019). "In an ApoE-/- mice model of atherosclerosis, this compound induced a change in atherosclerotic plaques composition, thus limiting their evolution towards an instable phenotype, strongly suggesting MMP12 as a relevant target in this model." (PMID 31561608, 2019). "Here, we demonstrated a novel function of the miR-106b~ 25 cluster in regulating the progression of atherosclerosis in ApoE KO mice." (PMID 31796057, 2019).
atherosclerosis (continued). "The atherosclerosis model was established by feeding ApoE−/− mice with high-fat diet, and the levels of lncRNA MALAT1 in mouse arterial tissue were detected by RT-qPCR." (PMID 30871555, 2019). "Recently, APOE-knockout in rabbits has been shown to promote atherosclerosis and associated premature IVD degeneration that mimic the symptoms of atherosclerosis and structural changes of IVDs in humans." (PMID 31751427, 2019). "Our current data demonstrate that LPS, which cooperates with ox-LDL and induces IRF1 activation, exacerbates the pathogenesis of atherosclerosis in ApoE-/- mice." (PMID 31367250, 2019). "Previously, the GK+/−ApoE−/− mouse model has been developed as a model combining hyperlipidemia and hyperglycemia, which had impaired glucose tolerance and a minimal increase of atherosclerosis relative to ApoE−/− mice." (PMID 30949516, 2019). "ApoE KO mice treated with simvastatin were used as a positive group for evaluating potential anti-atherosclerosis lesions function of the peach kernel oil." (PMID 30669336, 2019). "Transfer of IgG purified from hyperlipidemic ApoE−/− mice increased atherosclerosis in contrast to transfer of IgG purified from normolipidemic mice, consistent with an atherogenic role of IgG in atherosclerosis." (PMID 31998318, 2019). "In agreement with a bradykinin-independent function of the B2 bradykinin receptor in atherosclerosis, treatment of ApoE–/– mice with the B2 bradykinin receptor-specific antagonist, HOE140, did not alter atherosclerosis progression." (PMID 30847343, 2019). "Irisin-ApoE-/- and ApoE-/- mice were used to study the metabolic function of Irisin in dyslipidemia and atherosclerosis." (PMID 31191305, 2019). "Compared to ApoE−/− mice, atherosclerosis at the aortic sinus in μMT−/−ApoE−/− mice was reduced by ~50% as assessed by intimal atherosclerotic lesion areas, without affecting lipid composition in the lesions." (PMID 31998318, 2019). "LCZ696 significantly ameliorated atherosclerosis and inflammation in apoE−/− mice compared with valsartan." (PMID 31019233, 2019). "In mice fed a high fat diet to induce atherosclerosis, those with Grn deletion combined with apolipoprotein E (apoE) knockout had enhanced atherosclerotic lesions compared to apoE knockout mice with intact Grn genes." (PMID 30862089, 2019). "In summary, dual neprilysin inhibitor–angiotensin II receptor blocker combination therapy with LCZ696 was superior to ang II receptor blockade with valsartan alone in suppressing atherosclerosis and inhibiting the inflammatory response in apoE−/− mice." (PMID 31019233, 2019). "In a previous study immunization against aldehyde-modified laminin, another extracellular matrix protein present in basement proteins, resulted in increased atherosclerosis in apoE−/− mice." (PMID 30979943, 2019). "In this study, we investigated the impact of the B2 bradykinin receptor on atherosclerotic lesion formation in hypercholesterolemic ApoE–/– mice as a model of atherosclerosis." (PMID 30847343, 2019).
atherosclerosis (continued). "More importantly, both chicory and its constitute protocatechuic acid have been documented to inhibit atherosclerosis in ApoE‐/‐ mice through similar mechanisms by promoting endothelium‐dependent vasodilation." (PMID 31572600, 2019). "To investigate the role of the B2 bradykinin receptor in atherosclerosis, we used hypercholesterolemic ApoE–/– mice as an experimental model of atherosclerosis." (PMID 30847343, 2019). "Aortic ROS generation in ApoE–/– mice was previously attributed to the atherosclerosis-enhancing function of the angiotensin II AT1 receptor, which generates ROS by activation of NADPH oxidases." (PMID 30847343, 2019). "To verify the expression of miR-181a during atherosclerosis, we first examined miR-181a-5p, as well as miR-181a-3p levels in aortic plaque and plasma of apoE−/− mice fed a high fat diet (HFD)." (PMID 31064980, 2019). "Genetic deficiency of IL-1 receptor 1 or treatment with anti-IL1β decreased atherosclerosis in the aortic sinus and total aorta of ApoE−/− mice." (PMID 31998318, 2019). "To date, most studies examining the effects of CLA supplementation on atherosclerosis have been performed in apoE−/− mice, somewhat limiting the translational knowledge gleaned by these mouse studies." (PMID 30754681, 2019). "In the models of atherosclerotic ApoE-/- mice, high-fat diet inhibits Beclin1-mediated protective effects of macrophage autophagy, thus accelerating the progression of atherosclerosis." (PMID 31080547, 2019). "The subunit GPIbβ has been also investigated in atherosclerosis by using GPIbβ−/−/ApoE−/− mice fed a chow diet for 30 weeks." (PMID 31572732, 2019). "CD248 was upregulated during atherosclerosis in apolipoprotein E (ApoE)– null mice and human atherosclerotic samples." (PMID 30847027, 2019). "Oral administration of calcitriol decreases atherosclerosis in ApoE−/− mice by decreasing macrophage accumulation and inducing T regulatory cells (Tregs) and immature dendritic cells with tolerogenic functions." (PMID 31623356, 2019). "Taken together, the high-fat diet-induced ApoE-/- mice showed typical pathological features of atherosclerosis which were then employed for subsequent experiments." (PMID 30926762, 2019). "Analyses of lesion areas clearly showed that atherosclerosis did occur in ApoE–/–/TP–/– mice, but to a lesser extent compared to that of ApoE–/– counterparts." (PMID 31611817, 2019). "In diabetic ApoE−/− mice model, cPKCβ can damage vascular endothelial cells through the IL-18/IL-18 binding protein pathway, promote the formation of atherosclerosis, and cPKCβ inhibitor can relieve the progression of atherosclerosis." (PMID 31521120, 2019). "It has been reported that TREM-1 promoted atherosclerosis via monopoiesis, pro-inflammatory cytokine release, and foam cell formation in ApoE KO mice." (PMID 31275318, 2019). "SMYAD was reported to reduce the atherosclerosis plaque area, promote the recruitment of vasa vasorum pericytes, and stabilize atherosclerosis vulnerable plaques in ApoE-/- mice." (PMID 31619988, 2019). "In conclusion, we found DNA methylation in ABCG1 and APOE to be related to ischemic stroke and atherosclerosis in a Chinese population." (PMID 31823830, 2019).